ATF2 (activating transcription factor 2)
Diseases named in the same sentence as ATF2 in open-access papers (continued):
Sharing a sentence is not in itself a finding about the gene and the disease.
Hypertension (1 paper, 2015). The presence of chronic increased pressure in the systemic arterial system. "No clear differences were observed between groups 2 and 3, indicating that hypertension is unlikely to affect the PERK-eIF2α-ATF2 pathway as the main pathway inducing ER stress." (PMID 25574192, 2015). "This indicates that under hypertension conditions, the main signaling pathway of MI/R injury does not change The PERK-eIF2α-ATF2 pathway remains the main pathway by which MI/R injury induces the expression of CHOP." (PMID 25574192, 2015).
hypopharyngeal squamous cell carcinoma (1 paper, 2025). "CREB, ATF-2, and c-Jun stimulate transcriptional activation of the prostaglandin endoperoxide synthase-2 promoter via the CRE in nitric oxide-stimulated hypopharyngeal squamous cell carcinoma." (PMID 40871473, 2025).
Impaired glucose tolerance (1 paper, 2016). An abnormal resistance to glucose, i.e., a reduction in the ability to maintain glucose levels in the blood stream within normal limits following oral or intravenous administration of glucose. "In this study, we found that tunicamycin-induced ER stress increased serum free fatty acid (FFA) and impaired glucose tolerance, elevated the mRNA levels of GRP78, Chop, ATF2 and caspase 3, but reduced adiponectin mRNA level in white adipose tissue." (PMID 27882945, 2016).
ischemia (1 paper, 2018). A hypoperfusion of the BLOOD through an organ or tissue caused by a PATHOLOGIC CONSTRICTION or obstruction of its BLOOD VESSELS, or an absence of BLOOD CIRCULATION. "Our results support the hypothesis that PKCε regulates phosphorylation and nuclear sequestration of ATF2 in hippocampal neurons during ischemia-induced neurodegeneration." (PMID 30497386, 2018).
laryngeal carcinoma (1 paper, 2017). Carcinoma that arises from the laryngeal epithelium. "The present study demonstrates that reduction of miR-26b is associated with chemoresistance in cisplatin-resistant laryngeal cancer cell model, and recovery of miR-26b is able to decrease this cisplatin resistance by targeting ATF2." (PMID 29108284, 2017). "We found that recovery of miR-26b in cisplatin-resistant laryngeal cancer inhibited interaction with ATF2 and c-Jun by decreasing the cellular level of ATF2." (PMID 29108284, 2017). "In summary, our study has provided several evidence that overexpression of miR-26b decreases the cisplatin-resistance in laryngeal cancer by targeting ATF2." (PMID 29108284, 2017). "We then proved that overexpression of ATF2 was responsible for cisplatin resistance in laryngeal cancer." (PMID 29108284, 2017). "In this study, we found that ATF2 was overexpressed in cisplatin-resistant laryngeal cancer cells." (PMID 29108284, 2017). "Therefore, cisplatin treatment induced higher level of phosphorylated ATF2 in these resistant laryngeal cancer cells." (PMID 29108284, 2017).
laryngeal squamous cell carcinoma (1 paper, 2023). A squamous cell carcinoma that arises from the larynx. "In addition, upregulation of Tiam1 expression could also promote radioresistance in laryngeal squamous cell carcinoma by activating the JNK/ATF-2 signaling." (PMID 36765039, 2023).
lymphocytic leukemia (1 paper, 2020). "By interacting with ATF2, one of AP-1 complex, c-Jun, has been found to play an important role during apoptosis progression in lymphocytic leukemia cells and participates in drug responses in AML cells." (PMID 33324412, 2020).
meconium aspiration syndrome (1 paper, 2025). A serious condition in which a newborn breathes a mixture of meconium (the first intestinal discharge) and amniotic fluid into the lungs around the time of delivery. "Complete loss of Atf2 leads to early post‐natal lethality characterized by the meconium aspiration syndrome." (PMID 39949985, 2025).
mucormycosis (1 paper, 2019). "atf1 and atf2 genes induce pathways related to virulence processes in mucormycosis." (PMID 30723131, 2019).
myeloid leukemia (1 paper, 2012). A clonal proliferation of myeloid cells and their precursors in the bone marrow, peripheral blood, and spleen. "SAPK is associated with the molecular response of myeloid leukemia cells to TPA, through the phosphorylation and activation of c-jun, activating transcription factor 2 (ATF2) and Elk-1, contributing to the induction of the c-jun and Erg-1 early response genes involved in this signaling process." (PMID 23109817, 2012).
nasopharyngeal carcinoma (1 paper, 2026). A carcinoma arising from the nasopharyngeal epithelium. "Additionally, via its DNA-binding domain, EBNA1 binds to host gene promoters, notably upregulating c-Jun and ATF2 which is critical for nasopharyngeal carcinoma (NPC) development and metastasis." (PMID 41607541, 2026).
non-alcoholic fatty liver disease (1 paper, 2023). "ATF2 has been previously linked to non-alcoholic fatty liver disease." (PMID 37415213, 2023).
oral cancer (1 paper, 2016). "Genetic predisposition to oral cancer with concomitant increase in TGF-β and oncogenic molecules such as c-Jun; ATF2 in OSF may signify progression to oral squamous cell carcinoma (OSCC)." (PMID 27708346, 2016).
oropharyngeal cancer (1 paper, 2025). Carcinoma, predominantly squamous cell, arising from the epithelial cells of the oropharynx. "While CpG sites annotated to ATF2 were overall hypomethylated across oropharyngeal cancer samples, mean methylation levels showed a significant positive correlation (r = 0.03, p = 0.007) with gene expression." (PMID 41301032, 2025).
osteoporosis (1 paper, 2019). A condition of reduced bone mass, with decreased cortical thickness and a decrease in the number and size of the trabeculae of cancellous bone (but normal chemical composition), resulting in increased fracture incidence. "Based on previous studies, ATF2, FBXW7, and RDX were osteoporosis-related DEGs." (PMID 30809532, 2019).
periodontitis (1 paper, 2022). An acute or chronic inflammatory process that affects the tissues that surround and support the teeth. "Meanwhile, researchers have found that ATF2 is related to the occurrence of aggressive periodontitis." (PMID 35901060, 2022).
pituitary adenomas (1 paper, 2021). "In line with this postulation, there is some evidence to suggest that phosphorylated AMPK/ATF2 is involved in tumorigenesis in GH secreting pituitary adenomas." (PMID 34295309, 2021).
poliovirus infection (1 paper, 2015). An disease or disorder caused by infection with Enterovirus C. "The results demonstrate that poliovirus infection results in the activation of both ATF-2 and NF-κB but very little activation of IRF-3." (PMID 26437794, 2015). "The results show that poliovirus infection results in induction of very low levels of IFN-β mRNA despite clear activation of NF-κB and ATF-2." (PMID 26437794, 2015).
prediabetes (1 paper, 2023). "We conclude that PAK1 is essential for muscle mitochondrial function, and it is mediated through a p38MAPK/ATF2/PGC1α-axis signaling pathway, providing a new signaling cascade for potential therapeutic interventional strategies to skeletal muscle insulin resistance in prediabetes and T2D." (PMID 37759961, 2023).
preeclampsia (1 paper, 2024). Preeclampsia is a hypertensive disorder of pregnancy that is characterized by new-onset hypertension with proteinuria presenting after 20 weeks of gestation, and depending on mild or severe forms may initially present with severe headache, visual disturbances, and hyperreflexia. "Both ATF2 and STAT3 are associated with preeclampsia; studies indicate that elevated levels of ATF2 characterize preeclamptic women, normalizing after low-dose aspirin interventions." (PMID 39596234, 2024).
prion disease (1 paper, 2010). A transmissible disease that is caused by a protein that is able to induce abnormal folding of normal cellular proteins, leading to characteristic spongiform brain changes, which are associated with neuronal loss without an inflammatory response. "c-Fos can suppress the expression of c-Jun/ATF2 which promotes neuronal apoptosis, while NF-KappaB may have a role in prion diseases through the inflammatory response." (PMID 20862290, 2010).
pulmonary fibrosis (1 paper, 2021). Chronic progressive interstitial lung disorder characterized by the replacement of the lung tissue by connective tissue, leading to progressive dyspnea, respiratory failure, or right heart failure. "ATF2 regulates the expression of JUN through homo-dimerization or hetero-dimerization, consequently, might control pulmonary fibrosis." (PMID 34603282, 2021).
renal carcinoma (1 paper, 2022). A carcinoma arising from the epithelium of the renal parenchyma or the renal pelvis. "Similarly, the activation of ATF2 predicted poor prognosis and promoted the malignant phenotypes in renal cancer cells." (PMID 36009381, 2022).
Renal cyst (1 paper, 2016). A fluid filled sac in the kidney. "Currently, the role of ATF2 in the physiology and pathology of kidney is limited to the evidence that ATF2 has been demonstrated to play a key role in the morphogenesis and apoptosis of renal epithelial cells, possibly resulting in renal cyst formation." (PMID 27377902, 2016).
renal fibrosis (1 paper, 2021). A final common manifestation of a wide variety of chronic kidney diseases characterized by glomerulosclerosis and tubulointerstitial fibrosis. "Studies have shown that JNK dependent phosphorylation of ATF2/c-Jun transcription factors resulting in TGF-β transcription play the important roles in the formation of oral submucous and renal fibrosis." (PMID 33806765, 2021).
Stroke (1 paper, 2012). Sudden impairment of blood flow to a part of the brain due to occlusion or rupture of an artery to the brain. "Interestingly, following axotomy, ATF2 is reduced in the dorsal motor nucleus of the vagus nerve and in the hypoglossal nucleus in rats, and it is upregulated in sprouting cortical neurons following stroke." (PMID 23236355, 2012).
systemic sclerosis (1 paper, 2014). A chronic disorder, possibly autoimmune, marked by excessive production of collagen which results in hardening and thickening of body tissues. "ATF2 is observed as a serological marker for inflammation and lung involvement in systemic sclerosis (SSc)." (PMID 25049453, 2014).
varicella-zoster virus infections (1 paper, 2016). "In varicella-zoster virus infections, both p38 MAPK and JNK are activated, thereby activating of the downstream signal ATF2." (PMID 26901653, 2016).
tumor (109 papers, 2008 to 2026). "ATF2 was also an oncogene that is associated with the progression and resistance to anti-tumor therapy, including HNSCC." (PMID 38157249, 2023). "Obviously, the ATF2 effects are strongly dependent not only on the experimental stimulus and the tumor type but also on the combination of different mutations in a given cell." (PMID 37237279, 2023). "Here, we identified a novel ATF2-dependent mechanism underlying tumor invasiveness in CRC in vitro, in vivo, and in silico." (PMID 35838828, 2022). "Our study reveals a novel and important mechanism for the regulation of TROP2 expression via ATF2, mechanistically explaining the increased invasive potential of ATF2-deficient tumor cells." (PMID 35838828, 2022). "High ATF2 expression was associated with larger tumor size (p = 0.007), advanced pathological stage (p = 0.024), tumor thrombus (p = 0.032) and distant metastasis (p = 0.022)." (PMID 27377902, 2016). "The cytosolic localization of ATF2 has been associated with tumor suppressor activity in some solid tumors." (PMID 25852302, 2015). "The role of ATF2 proteins in cancer depends on cell context, as these factors have been associated with both oncogenic or tumor suppressive functions." (PMID 23966864, 2013). "Knock-in mice expressing a form of ATF2 that cannot be phosphorylated by ATM are more susceptible to tumor development." (PMID 21203491, 2010). "Accumulating studies demonstrated ATF2 is implicated in tumor progress." (PMID 37816820, 2023). "In contrast, the majority of HCT116-derived tumors had a predominantly cohesive pushing front that clearly segregated tumor cells from the surrounding muscle layer with only minor focal invasions, suggesting that the loss of ATF2 remarkably alters the invasion pattern." (PMID 35838828, 2022). "Several studies concluded that the sub-cellular localization of ATF2 might be linked with human tumor stage and patient’s survival prognosis." (PMID 35641966, 2022). "The presence of disseminating ATF2-KO tumor cells in the brain of chicken might underline the potential of ATF2-KO cells to spread to multiple and more unusual sites." (PMID 35838828, 2022). "Moreover, high expression levels of MAPK14 or ATF2 were associated with advanced tumor stages and a more de-differentiated histological grading." (PMID 33803354, 2021). "Thus, ATF2 might be closely linked to tumor invasiveness in CRC; however, the pathway remains unknown." (PMID 35838828, 2022). "Hence, ATF2 recruitment to the mitochondria is associated with its tumor suppressor activities." (PMID 25852302, 2015). "Several studies have demonstrated low ATF2 levels correlated with poor prognosis and tumor aggressiveness in CRC patients." (PMID 37280630, 2023). "In contrast, cancer cells showing low ATF2-dependent activity were significantly less invasive both at the front of primary tumours and in metastatic lesions." (PMID 36621522, 2023). "Throughout the metastatic cascade β-catenin/TCF-dependent and ATF2-dependent signalling pathways appear to complement one another, being active in distinct zones within the primary tumour and in metastatic lesions." (PMID 36621522, 2023). "ATF2, as a transcription factor of the leucine zipper family, behaves as a tumor suppressor or as an oncogene in a context- and stimulus-dependent manner." (PMID 37237279, 2023). "In a previous paper, we already described in TE7 esophageal cells that oxidative stress-induced apoptosis was enhanced in tumor cells with decreased ATF2 levels." (PMID 37237279, 2023). "Obviously, one tumor suppressor, ATF2, is sufficient to regulate the ATR-Chk1 interaction under physiological conditions." (PMID 37237279, 2023). "The role of ATF2 in damage repair has already been highlighted in tumor cells treated with ionizing radiation." (PMID 37237279, 2023).
tumor (continued). "In contrast, other studies have postulated that ATF2 plays a tumor suppressive role in estrogen receptor-positive breast cancer." (PMID 37955015, 2023). "In contrast ATF2-dependent signalling is active in most invasive cells, both in primary tumours and in metastatic lesions." (PMID 36621522, 2023). "In clear contrast, invading cancer cells maintained relatively high levels of ATF2-dependent reporter activity (ATF2pos), both within the metastatic lesions and in primary tumours." (PMID 36621522, 2023). "As observed in vitro, the majority (>90%) of HT1080 cells in primary tumours displayed moderate ATF2-dependent GFP reporter activity (ATF2pos; green to red signal average ratio >1.5)." (PMID 36621522, 2023). "In contrast, high ATF2-dependent signalling promotes cancer cell invasion out of the primary tumour and dissemination to secondary sites of metastasis." (PMID 36621522, 2023). "β-catenin/TCF-dependent signalling is downregulated during primary tumour invasion and intravasation (Fig. 7Fii), while a sufficient level of ATF2-dependent activity is maintained." (PMID 36621522, 2023). "ATF2 has a highly divergent character, and can either drive or block tumor progression in a tissue- and stimulus-dependent manner." (PMID 35838828, 2022). "A shift in the growth pattern upon ATF2 loss was also observed in HT29-KO cells, suggesting that tumor cell de-adhesion is increased when ATF2 is lost." (PMID 35838828, 2022). "We report that low ATF2 levels correlated with worse prognosis and tumor aggressiveness in CRC patients." (PMID 35838828, 2022). "Emerging evidence has confirmed that ATF2 can exert oncogenic or tumor suppressor activities depending on the cell or tissue in which it is expressed." (PMID 35641966, 2022). "Current studies suggest that ATF2 can exert oncogenic activities or tumor suppressor function depending on the tissues or cell type." (PMID 35641966, 2022). "The activation and impact of ATF2 in cisplatin treated cells were evaluated with western blot, incucyte live cell analysis, clone formation and tumor xenografts assays." (PMID 35641966, 2022). "The results reveal that knockdown of lncRNA TTN-AS1 downregulated the expressed level of ATF2 and ki67 in our in vivo T24 tumor xenografts." (PMID 34671381, 2021). "Previously, several studies have reported ATF2 was highly expressed in several types of tumors and served as a tumor promotor, including HCC." (PMID 34513693, 2021). "ATF2 is a mediator of carcinogenesis of several types of neoplasms which can be phosphorylated by ERK on Thr71." (PMID 33919565, 2021). "ATF2 is reported to play two roles in different types of tumors during tumor progression, namely, tumor-promoting genes and tumor-suppressor factors." (PMID 34671381, 2021). "In terms of mechanism, TTN-AS1 can promote the proliferation and invasion of tumor cells by regulating the level of downstream factor ATF2." (PMID 34671381, 2021). "In summary, TTN-AS1 plays a role as a tumor-promoting factor in the progression of BC and can positively regulate the proliferation and invasion of BC cells by regulating the expression of ATF2." (PMID 34671381, 2021). "Off note, different upstream activation pathways of ATF2 induce different, partly divergent downstream effects, and therefore, ATF2 is considered as a transcription factor that elicits both oncogenic or tumor suppressor activities." (PMID 33803354, 2021). "The apparent dual function of ATF2 has been also observed in skin tumourigenesis, where ATF2 has both oncogenic and tumour-suppressive activities." (PMID 33198803, 2020). "At the individual gene level, the nuclear orphan receptor NR2F6 together with the transcription factor ATF2 emerged as the most significant mutually exclusive gene pair in pan-tumor analysis." (PMID 32117236, 2020).